IL13 (interleukin 13)
Diseases named in the same sentence as IL13 in open-access papers (continued):
Sharing a sentence is not in itself a finding about the gene and the disease.
infection (continued). "During infection, IL-13 induces eotaxin production, thereby recruiting eosinophils into the tissue, where they are maintained by locally produced IL-5 and secrete factors that contribute to type 2 inflammation." (PMID 38277692, 2024). "In a murine model of infection with the nematode Nippostrongylus brasiliensis, IL-13 was shown to inhibit the expression of IL-18, an inflammasome-activated cytokine that contributes to inflammation a cell death via pyroptosis." (PMID 38374922, 2024). "Unsurprisingly, we found elevated ll-4 and Il-13 expression in the HbTg compared to Tg infected animals at day 5 post Tg infection in the MLN." (PMID 38950025, 2024). "While IL‐13 KO had less HA in response to infection, the amount of alveolar epithelium damage (defined by mean linear intercept analysis) was increased in KO mice." (PMID 39606183, 2024). "Resistant sheep had consistently higher IL-13 production which changed significantly between the first and second challenge infections." (PMID 38338687, 2024). "There was a significant (not for il-5 in the LB group) increase in the expression of il-5 and il-13 in all three infection groups compared to uninfected mice, with the PR group reaching the highest levels." (PMID 39466851, 2024). "On day 6 of infection, the study found elevated IL-4, IL-5, IL-13, and IL-10 levels in infected mice." (PMID 38166140, 2024). "Collectively, these data suggest that basophil-derived IL-4 and IL-13 control the activation and proliferation of MCs after P. y. yoelii 17XNL infection." (PMID 38780542, 2024). "These cells expand robustly after infection with intestinal parasites such as N. brasiliensis or in response to exogenous IL-33 or IL-25, and they are the major innate IL-13 resources under these conditions." (PMID 39559705, 2024). "L. brevis 23017 improved SIgA levels by regulating the level of IL-5, IL-13, pIgR, J-chain and IgA α-chain to enhance the immune function against S. typhimurium C7731 infection." (PMID 38930517, 2024). "During the time course of infection, the Th1 immune response alters to a Th2 response, with increased levels of IL-4, IL-5, and IL-13." (PMID 39329761, 2024). "At P15, treatment x sex analysis revealed sex-specific effects of infection on both of these inflammatory mediators (treatment x sex, IL-13; F = 5.820, p = 0.026, KCNN4; F = 7.661, p = 0.010)." (PMID 38879567, 2024). "At d7 p.i., the infection‐induced accumulation of HA in lung homogenate was significantly reduced in IL‐13 KO mice (compared to infected WT littermate controls)." (PMID 39606183, 2024). "A study performed using H. contortus in lambs confirmed that there was an obvious rise in IL-4 and IL-13 levels in the abomasal mucosae following the infection." (PMID 38338687, 2024). "Our results showed increased in IFN-γ levels and decreased IL-4 and IL-13 with treatment with Linex, Albendazole or both during the muscular phase of infection." (PMID 39609767, 2024). "In comparison to L. major, L. braziliensis induces significantly lower expression of IL-4, IL-10, and IL-13 in the early phase of infection in BALB/c mice." (PMID 38543944, 2024). "Intestinal infection characteristically induces T-helper- 1 cell (Th1) cytokines early in infection followed by a gradual increase cytokines released by T-helper 2 cells such as IL-4 and IL-13, which play a crucial roles in the expulsion of the worms." (PMID 39609767, 2024). "Specifically, there was an increase in the levels of the cytokine IL-5 and IL-13 in relation to the number of exposures to infection, as well as an increase in these cytokines related to the increase in the dose of infection." (PMID 39621794, 2024). "As a surrogate of host response to infection with H. diminuta, infected mice showed increased concanavalin-A (con-A) stimulated splenic production of IL-4, IL-10, and IL-13, the variability in the data reflecting the individual mouse’s response to the worm." (PMID 39083533, 2024).
infection (continued). "For example, previous infection with T. spiralis leads to ILC2-derived IL-13-mediated upregulation of MUC5B/AC in the lung, thereby trapping N. brasiliensis independently of adaptive immunity." (PMID 38277692, 2024). "A significant difference in intestinal worm burdens between IL-13−/−and wild-type (WT) mice at two weeks post-infection (62 vs. 47 worms, p < 0.01) was observed." (PMID 39596084, 2024). "Lung CD4+ T cells displayed significantly increased Th1 (IFNγ) and Th2 (IL-4, IL-5, IL-13) cytokine production potential during pre-patent infection at the higher dose." (PMID 37012228, 2023). "CD4+ T cells play a pivotal role in infection, inflammation, and autoimmunity through cytokine release, including IL-4, IL-13, and IL-17, which induces a cascade of reactions that act against allergens." (PMID 36980282, 2023). "Our results support that the cytokine responses after short induction by IL-4/IL-13 can already interfere with TJ development which, in turn, correlates with enhanced infection efficiency, suggesting that the Th2 cytokines can target the TJs rather early." (PMID 37289055, 2023). "Following F. tularensis LVS infection, we detected only minimal expression of the type 2 cytokine IL-13 by ILCs." (PMID 36602520, 2023). "In contrast, levels of Th2 type cytokines (IL-4 and IL-13) in Tigit-/- mice were lower than those in WT mice at 4 weeks post infection." (PMID 36930687, 2023). "Accordingly, mRNA‐expression levels of anti‐inflammatory cytokines (IL‐4 and IL‐13) were increased in Bsep−/− mice upon infection." (PMID 37641872, 2023). "In the experiments against N. brasiliensis, it has been shown that, after 5 days of infection, the IL-25 activated iILC2s to highly express IL-13, IL-5 and IL-4, and only the iILC2s expressed the Th2 cytokines." (PMID 37173731, 2023). "Surprisingly, we found that IL-4, IL-5, IL-6, IL-10, and IL-13 levels reached peaks after 30 days of infection and then decreased in a time-dependent manner." (PMID 37691941, 2023). "ILC2 exhibited a moderate reduction in intrinsic capacity to produce IL-5 and IL-13 in response to infection; however, when coupled with decreased cellularity, this led to an overall reduction in the number of cytokine-producing ILC2." (PMID 36571761, 2023). "For instance, genetic variants in IL13, IL4, IL10, IFNG and STAT6 genes were associated not only with infection intensities and re-infection of S. mansoni after treatment, but also with S. haematobium infections and its infection intensities." (PMID 36889485, 2023). "TNF-α, IL-10, IL-13, and IL-33 were significantly (p < 0.05) increased in severe infection comparison to a mild infection in children with HRSV coinfection with HBoV." (PMID 37239461, 2023). "Whereas, IL-10, IL-13, and IL-33 were significantly (p < 0.05) increased in severe infection compared to a mild infection in children with HBoV." (PMID 37239461, 2023). "Exogenous IL-13 has been demonstrated to exert a hypoalgesic effect on mice infected with L. major and exacerbate the course of infection." (PMID 37908348, 2023). "Whereas, IL-10, IL-13, and IL-33 were significantly increased in severe infection in compared a mild infection in children with HBoV." (PMID 37239461, 2023). "Intriguingly, after 30 days of infection, the levels of all cytokines decreased significantly over time, yet anti-inflammatory cytokines (IL-4, IL-5, IL-10 and IL-13) decreased to a lesser extent." (PMID 37691941, 2023). "The infection manipulates the cytokine network by affecting T-cell cytokines, IL-13 and correlation with other key cytokines and chemokines." (PMID 37242334, 2023). "Homozygous Il13eGFP mice, which lack IL-13, had a reduced expansion of LCMs during infection along with an MNP compartment, which was dominated by recruited MNPs at the expense of LCMs, thus making these mice more BALB/c-like." (PMID 36948193, 2023).
infection (continued). "After treatment with IL-4/IL-13 at day 1 followed by infection 24 h later, we observed increased intensities of ICP0 stainings compared to untreated cultures supporting enhanced efficiency of infection." (PMID 37289055, 2023). "Further, lung CD4+ T cells had significantly increased Th1 (IFNγ) and Th2 (IL-4, IL-5, IL-13) cytokine production potential during patent schistosome infection, at a greater magnitude than observed in pre-patent infection." (PMID 37012228, 2023). "rL. lactis treatment prior to infection with C. perfringens led to temporal and spatial changes in expression of IL-13, IL-17, IL-18, IL-22, IL-12p40 and IFN-γ to β-actin from week 1 onwards in all sites along the intestine." (PMID 38164397, 2023). "More importantly, adiponectin pretreatment of Caco2 cells prevented T. spiralis larval invasion in vitro and its administration during infection enhanced intestinal IL-13 secretion and worm expulsion in vivo." (PMID 37635188, 2023). "IL-13 has been suggested to protect against infection by promoting cell turnover and excreting infected epithelial cells." (PMID 37520555, 2023). "On the other hand, it was shown that NF-κB activation aided in infection eradication by triggering Th2 cytokine responses (mostly IL-9 and IL-13)." (PMID 37737322, 2023). "We observed increased levels of circulating IL-4 and IL-13 in animals that succumbed to lethal EVD, compared to relatively low levels of IL-13 in animals that survived infection." (PMID 36914721, 2023). "In late-phase infection, the elevated IL-4 and IL-13 activate the alternative macrophage pathway (M2), which can produce molecules that are toxic to the fluke and contribute to fibrosis and tissue repair." (PMID 37152685, 2023). "ILC2s themselves also upregulate CGRP during infection, which mediates autoinhibition of IL-13 expression." (PMID 37336989, 2023). "Whereas, IL-10, IL-13, and IL-33 were significantly increased in severe infection compared to mild infection in children with HBoV." (PMID 37239461, 2023). "Conversely, infection significantly reduced levels of IL-1α, IL-2, IL-9, IL-10, IL-12 (p70), IL-13, IFNγ, IL-3, CCL4 (MIP-1β), CSF 2 (GM-CSF), CCL5 (RANTES), and TNFα." (PMID 37790429, 2023). "Pro-inflammatory cytokines (IL-6, IFNγ, TNFα, and IL-12p40) as well as the anti-inflammatory cytokine IL-13 increased, whereas release of IL-1Ra (an IL-1β inhibitor) was reduced by infection with the mutant strain." (PMID 37669276, 2023). "The current study also reported that IL-10, IL-13, and IL-33 were significantly increased in severe infection compared to mild infection in children with HBoV." (PMID 37239461, 2023). "Consistent with changes in the T cell response, Il5 and Il13 gene expression in unfractionated duodenal tissue increased upon infection but was curtailed by IL-10R1 blockade, becoming similar to levels seen in naïve mice." (PMID 35428872, 2022). "Further TCR-based stimulation induced increased levels of IL-13 production from PZQ-treatment exposed offspring during cognate infection (Supplement 3)." (PMID 35833137, 2022). "This particular role of IL‐13 is supported by its recently described function in SARS‐CoV‐2 specific recall responses after infection and vaccination." (PMID 36271745, 2022). "Conversely, anti-inflammatory cytokines, such as IL-4, IL-5, IL-10 and IL-13, among others, seem to act to regulate the Th1-type response and favoring the development of infection." (PMID 35891310, 2022). "It has been recognized that IL-4 and IL-13 cytokines mediate the goblet cell hyperplasia during the gut infection, which the latter plays a significant protective role against the infection." (PMID 36035429, 2022). "For example, chronic infection of adult mice with a mouse parainfluenza virus leads to NKT cell- and IL-13-dependent alternative activation of macrophages which is first detected 21 days after infection." (PMID 36032072, 2022).
infection (continued). "Taken together, these results implicate a critical role for IL‐13 in the aftermath of SARS‐CoV‐2 mild infections and mRNA vaccinations, conferring protection against airway directed, atopic side reactions that occur in mildly experienced COVID‐19." (PMID 36271745, 2022). "The results, taken together, show that ex vivo infection with HSV-1 revealed successful viral penetration in IL-4/IL-13-stimulated skin, supporting that the virus can gain access via the external skin surface due to the Th2 cytokine-induced modifications." (PMID 35969080, 2022). "The infection results in the differentiation of Th2 cells releasing interleukin-4 and IL-13 along with strong B cells responses primarily characterized by IgG1 production." (PMID 35690651, 2022). "Here, we stimulated healthy skin with IL-4/IL-13 prior to infection to explore the impact of the Th2 cytokine responses on HSV-1 invasion." (PMID 35969080, 2022). "It has been shown that type 2 cytokines IL-4 and IL-13 can increase infection of monocytes and monocyte-derived dendritic cells (MoDCs) by upregulating MMR69,70." (PMID 35869167, 2022). "Praziquantel treatment completely abrogated infection-induced IL-13 levels in both treatment groups (IN-PZQ and ILP-PZQ)." (PMID 35839247, 2022). "At the start of infection (i.e., 3 d from the start of IL-13 treatment), goblet cells had increased in size and number in response to the cytokine." (PMID 35353667, 2022). "Reduced epithelial damage coincided with reduced anoikis and limited spread of infection in IL-13–treated HAE cell cultures." (PMID 35353667, 2022). "IL-33 production and the number of type-2 innate lymphoid cells differ greatly after RSV infection based on age: neonatal mice produce more IL-13 and IL-33 in response to infection than adult mice, as well as the number of type-2 innate lymphoid cells." (PMID 35327516, 2022). "We also found that in splenic T cells of WT mice, infection obviously upregulated Th2 cytokines such as IL-4, IL-10, and IL-13." (PMID 35666747, 2022). "In our study, infection with B.1.351 elevated the levels of IFN-γ, TNF-α, IL-13, and IL-10, whereas infection with GD108 elevated the level of IL-17 in macaques." (PMID 36069561, 2022). "Upon infection with helminths, intestinal epithelial cells produce alarmins (e.g., IL-25) and activate ILC2s to secrete IL-13, which induces differentiation of intestinal stem cells into tuft and goblet cells, important for parasite expulsion." (PMID 36430676, 2022). "We found that FXR deficiency in hepatocytes promoted the progression of liver injury, aggravated weight loss and death caused by infection, and promoted inflammatory cytokines production, such as IL-6, IL-1β, TNF-α, IL-4, IL-10, and IL-13." (PMID 35930537, 2022). "All tissues showed increased production of IL-4, IL-5 and IL-13 from wk 6, which either peaked at 8-12 wks post infection or remained elevated into chronic stages." (PMID 35958580, 2022). "Among Th2 cytokines in the mouse lung, we found that the levels of all four marker cytokines (IL-4, IL-6, IL-10, and IL-13) progressively increased with infection time; similarly, the levels of IL-6, IL-10 and IL-13 were upregulated in the mouse brain." (PMID 35617354, 2022). "NB and TM infection models have in common that intestinal tuft-cell derived IL-25 promotes IL-13 release by ILC2s, which in turn elicits further expansion of IL-25 producing tuft cells." (PMID 36430676, 2022). "The IL-4 and IL-13 genes reside only 13 kb apart and coordinate regulation of them determines the typical immune responses observed during infection." (PMID 35745240, 2022). "Intestinal ILC2 colocalize with adrenergic neurons and β2AR deficiency results in accumulation of IL-13 expressing ILC2, aggravated eosinophilia and a concomitant reduction in worm burden upon infection with N. brasiliensis." (PMID 36045216, 2022).
infection (continued). "Compared to RV-A1B infection, the inflammatory response to RV-C15 is characterized by greater eosinophils, epithelial-derived innate cytokines and IL-13-producing ILC2s." (PMID 33968043, 2021). "Intriguingly, this analysis identified the enzyme Has1, which was upregulated during infection, as the most downregulated gene following IL-13 neutralization." (PMID 34185704, 2021). "A rapid and significant increase in regenerative IL13- and Arg1-releasing Ly6Clo monocytes upon infection was identified as being involved in abscess recovery." (PMID 33829283, 2021). "We confirmed that lung CD4+ T cells in our Il13−/− mouse strain expressed eGFP in lieu of functional IL-13 after infection with N. brasiliensis when compared with controls." (PMID 34127548, 2021). "In our study, ST2-/- mice decreased the concentration of IL-5 and increased IL-33, IL-13 and IL-17 in the initial stage of infection, and with 63dpi in addition to IL-33 and IL-17, also increased IL-1β concentration." (PMID 34324507, 2021). "A previous study showed that phosphorylated STAT5 (p-STAT5) was a key downstream molecule of the PD-1 signaling pathway in ILC2s and inhibited IL-5 and IL-13 expression in the context of infection with Nippostrongylus brasiliensis." (PMID 34194433, 2021). "CAGE transcriptomics showed up-regulated expression of IL-4i1 in IL-4- or IL-4/IL-13–prestimulated BMDMs 4 hours after infection with HN878 Mtb." (PMID 34739044, 2021). "Type 2 cytokines, such as IL-4 and IL-13, trigger a specialized macrophage phenotype; more regulatory and anti-inflammatory macrophages, which is necessary for the adequate infection control." (PMID 34502521, 2021). "In the serum, only IL-10 and IL-13 were significantly increased, while in urine IFN-γ, TNF-α, IL-13, IL-1β, IL-22, and IL-10 were significantly increased in by infection." (PMID 34662329, 2021). "A study evaluated histone acetylation in individuals exposed to A. lumbricoides found that histone acetylation levels in IL-4 and IL-13 genes were altered by infection." (PMID 33692795, 2021). "In this study, we examined the function of IL-13 during the early stages of infection with the lung-migrating nematode parasite Nippostrongylus brasiliensis." (PMID 34127548, 2021). "In chronically infected mice, at week 17 post infection, there was a significant positive correlation between numbers of lung eggs and expression of the Th2 cytokine IL-13, suggesting eggs are driving a pulmonary type-2 response." (PMID 33953712, 2021). "In primary infection, IL-13 is only involved in parasite expulsion after the parasites have already cleared the lung tissue." (PMID 34127548, 2021). "Five genes have been associated with both fibrosis and intensity of infection (RNASE3, IL4, IL10, IFNGI, and IL13)." (PMID 33659002, 2021). "Though we have yet to examine a role for IL-33 in the neonatal immune response to infection, we have detected both IL-13 and IL-5 within the BALF of P. murina infected BALB/c neonates." (PMID 34682248, 2021). "Although T helper cells play a central role in the induction of a protective immune response against infections from viral pathogens, Th2 cells producing interleukin (IL)-4, IL-13 and IL-5 can be detrimental in an infection." (PMID 33924141, 2021). "Our findings in human infection largely concur with earlier findings in the mouse model, specifically chronically elevated IL-13 and TNFα in the bladder tissue of egg-injected mice and only transient changes in IL-17." (PMID 34662329, 2021). "Clca1, Muc5ac, and Ccl11 were confirmed to be highly up-regulated during infection in WT mice but impaired in Il13−/− mice." (PMID 34127548, 2021). "IL-4 and IL-13 share a common receptor, IL-4Rα, whose effects in CL have been widely studied in L. major infection and to some extent during L. mexicana infection." (PMID 35154068, 2021).